DMPK (DM1 protein kinase)
Diseases named in the same sentence as DMPK in open-access papers (continued):
Sharing a sentence is not in itself a finding about the gene and the disease.
myotonic dystrophy type 1 (continued). "Myotonic dystrophy type 1 is caused by CTG repeat expansions in the 3′ UTR of DMPK." (PMID 32197402, 2020). "The number of cytosine-thymine-guanine (CTG) repeats (‘CTG expansion size’) in the 3′untranslated region (UTR) region of the dystrophia myotonica-protein kinase (DMPK) gene is a hallmark of myotonic dystrophy type 1 (DM1), which has been related to age of disease onset and clinical severity." (PMID 32645888, 2020). "The most significant SNP was rs527221, a nonsynonymous variant in the DMPK gene, which is responsible for causing type 1 myotonic dystrophy, severe childhood forms of which have been associated with ASD (Ekström, Hakenäs‐Plate, Samuelsson, Tulinius, & Wentz, 2008)." (PMID 30008175, 2018). "Myotonic dystrophy type 1 (DM1) is a multisystemic disorder with an autosomal dominant inheritance caused by an expansion of a CTG trinucleotide repeat in the 3′ untranslated region of the DMPK‐gene on chromosome 19q13.3." (PMID 29744165, 2016). "Mutations in the DMPK gene, causing the myotonic dystrophy type 1, were excluded." (PMID 27017278, 2016). "Myotonic dystrophy type 1 (DM1) is caused by an expanded CTG repeat in the DMPK gene, resulting in mutant transcripts that form expanded CUG (CUGexp) RNA foci and sequester muscleblind-like (MBNL) RNA-binding proteins." (PMID 41855125, 2026). "Myotonic dystrophy type 1 (DM1) results from the toxicity of RNA produced from the mutant allele of the DMPK gene." (PMID 41303468, 2025). "Myotonic Dystrophy Type 1 (DM1) is a complex multisystemic genetic disorder caused by CTG repeat expansions in the DMPK gene, leading to RNA toxicity and widespread splicing defects." (PMID 41303475, 2025). "Among these, we found 6 patients carrying pathogenic expansion in DMPK gene associated with myotonic dystrophy type 1 (DM1; MIM 160900)." (PMID 39775061, 2025). "For example, a large CTG repeat (NM_004409.5:c.*224CTG) in the 3′UTR of DMPK causes myotonic dystrophy type 1 (DM1) via a toxic gain-of-function mechanism." (PMID 40610610, 2025). "Myotonic Dystrophy type 1 (DM1) is a multisystem genetic disorder caused by unstable CTG expansions in the 3′-UTR of the DMPK gene." (PMID 41226794, 2025). "Myotonic dystrophy type 1 (DM1) is a multisystemic disorder caused by expanded CTG repeats in the 3′-UTR of the DMPK gene that lead to nuclear foci accumulation and splicing defects." (PMID 40896579, 2025). "Myotonic dystrophy type 1 (DM1) is an autosomal dominant disease caused by a CTG repeat expansion in the dystrophia myotonica protein kinase (DMPK) gene." (PMID 39932794, 2025). "Myotonic dystrophy type 1 (DM1) is an autosomal dominant disorder caused by an unstable expanded CTG repeat located in the 3′-UTR of the DM1 protein kinase (DMPK) gene." (PMID 38165037, 2024). "Myotonic dystrophy type 1 (DM1) is a rare neuromuscular disease caused by a CTG repeat expansion in the DMPK gene that generates toxic RNA with a myriad of downstream alterations in RNA metabolism." (PMID 37744174, 2023). "Myotonic dystrophy type 1 (DM1) is an autosomal dominant multisystemic disease caused by a CTG repeat expansion in the 3′-untranslated region (UTR) of DMPK gene." (PMID 37373276, 2023). "Myotonic dystrophy type 1 (DM1) is caused by an unstable expanded CTG repeat located within the 3′ untranslated region (3′ UTR) of the DMPK gene." (PMID 35563013, 2022). "Indeed, hypercholesterolemia and elevated TG have also been reported in LGMD type 1C (caveolin-3 mutations) and myotonic dystrophies types 1 and 2 (DMPK and CNBP mutations, respectively) — although often in the absence of control conditions or using experimental approaches." (PMID 36447272, 2022). "Myotonic dystrophy type 1 (DM1) is the most common autosomal-dominant disorder caused by the CTG repeat expansion of the DMPK, and it has been categorized into three phenotypes: mild, classic, and congenital DM1." (PMID 36011377, 2022).
myotonic dystrophy type 1 (continued). "Myotonic dystrophy type 1 (DM1) is an inherited neuromuscular disease caused by expanded CTG repeats in the 3′ untranslated region (3′UTR) of the DMPK gene." (PMID 34490258, 2021). "Myotonic Dystrophy type 1 (DM1) is an autosomal dominant disease is majorly caused by a toxic CTG repeat expansion in the UTR of the DMPK located on chromosome 19q13.3." (PMID 34827576, 2021). "Myotonic dystrophy type 1 (DM1) is caused by the expansion of a (CTG)n repeat sequence in the dystrophia myotonica protein kinase (DMPK) gene 3’UTR." (PMID 32340368, 2020). "Abnormally expanded CUG-repeats in the DMPK gene cause myotonic dystrophy type 1 (DM1) by sequestration of MBNL1 to nuclear RNA foci and by upregulation of another RNA-binding protein, CUG-binding protein 1 (CUGBP1)." (PMID 32054946, 2020). "This study employs the Leptotrichia shahii (Lsh) Cas13a and a repeat-based CRISPR RNA (crRNA) to track and eliminate toxic RNA aggregates in myotonic dystrophy type 1 (DM1) – a neuromuscular disease caused by CTG expansion in the DMPK gene." (PMID 33362853, 2020). "Myotonic dystrophy type 1 (DM1) is a complex neuromuscular disease caused by an unstable cytosine thymine guanine (CTG) repeat expansion in the DMPK gene." (PMID 31936870, 2020). "Specifically, myotonic dystrophy type 1 (DM1) is a multisystemic disorder caused by expanded CTG repeats in the DMPK gene which results in abnormal mRNA-splicing." (PMID 31010208, 2019). "Myotonic dystrophy type 1 (DM1) is a heritable disease caused by the expansion of genomically encoded CUG repeats in the 3′ untranslated region of the dystrophia myotonica protein kinase (DMPK) mRNA (Mirkin, 2007 ▸)." (PMID 31584014, 2019). "CTG expansions in DMPK gene, causing myotonic dystrophy type 1 (DM1), are characterized by pronounced somatic instability." (PMID 30546383, 2018). "Myotonic dystrophy type 1 (DM1) is caused by a CTG repeat expansion in the 3’ untranslated regions of DMPK on chromosome 19 and is characterized by progressive myopathy, myotonia and multi-organ involvement." (PMID 30521610, 2018). "Myotonic dystrophy type 1 (DM1) is a multi-systemic disorder caused by abnormally expanded stretches of CTG DNA triplets in the DMPK gene, leading to mutated-transcript RNA-toxicity." (PMID 29955039, 2018). "Myotonic dystrophy type 1 (DM1) is an autosomal-dominant multi-system disease caused by expanded CTG repeats in dystrophia myotonica protein kinase (DMPK)." (PMID 28211918, 2017). "Myotonic dystrophy type 1 (DM1) is an autosomal dominant genetic disease caused by expansion of a CTG microsatellite in the 3’ untranslated region of the DMPK gene." (PMID 26919350, 2016). "CUG repeat expansions in the 3′ UTR of dystrophia myotonica protein kinase (DMPK) cause myotonic dystrophy type 1 (DM1)." (PMID 25303993, 2014). "Myotonic dystrophy type 1 (DM1) is caused by the expansion of an unstable CTG repeat located in the 3′-UTR of (DMPK) the DM protein kinase gene." (PMID 24715907, 2014). "The pathogenesis of Myotonic Dystrophy type 1 (DM1) is linked to unstable CTG repeats in the DMPK gene which induce the mis-splicing to fetal/neonatal isoforms of many transcripts, including those involved in cellular Ca2+ homeostasis." (PMID 24705164, 2013). "Myotonic dystrophy type 1 (DM1) is caused by the abnormal expansion of a CTG repeat located in the DM protein kinase (DMPK) gene." (PMID 23209425, 2012). "Myotonic dystrophy type 1 (DM1) is a multi-systemic disorder caused by a CTG trinucleotide repeat expansion (CTGexp) in the DMPK gene." (PMID 22427994, 2012). "Expansion of a CTG repeat in the 3' UTR of the DMPK gene causes myotonic dystrophy type 1 (DM1) and the expansion of a CCTG repeat in intron 1 of the ZNF9 gene causes myotonic dystrophy type 2 (DM2)." (PMID 24704980, 2012).
myotonic dystrophy type 1 (continued). "Myotonic dystrophy type 1 (DM1) is caused by expansion of a CTG triplet repeat within the 3′ untranslated region (UTR) of DMPK, whereas myotonic dystrophy type 2 (DM2) results from expansion of a CCTG repeat within the first intron of ZNF9." (PMID 20174632, 2010). "Myotonic dystrophy type 1 (DM1), caused by a CTG repeat expansion mutation in the 3′UTR of the DMPK gene, presents primarily as a distal myopathy, affecting the face, neck, and distal limb muscles." (PMID 40811031, 2025). "Expansion of CTG triplet repeats in the 3ʹ UTR of the DMPK human gene leads to a disease called myotonic dystrophy type 1 (DM1 or Steinert disease)." (PMID 40860596, 2025). "Myotonic dystrophy type 1 (DM1) is a chronic progressive, autosomal dominant, inherited multisystem disorder caused by a mutation in the DMPK gene, leading to variable CTG-repeat expansions." (PMID 40932620, 2025). "In Type 1 Myotonic Dystrophy (DM1), the mutated DMPK mRNA is retained in the nucleus, where the expanded 3′ trinucleotide repeat forms nuclear hairpin structures." (PMID 41018201, 2025). "In contrast, FXN GAA expanded repeats in Friedreich’s ataxia patients show an expansion bias in the cerebellum, and skeletal muscle in Myotonic Dystrophy Type 1 present with much larger DMPK CTG expansions." (PMID 38396267, 2024). "Myotonic dystrophy type 1 (DM1), the most common muscular dystrophy in adults and children, is caused by a (CTG)n expansion within the 3′ untranslated region (3′UTR) of the dystrophia myotonica protein kinase (DMPK) gene." (PMID 38473933, 2024). "Myotonic dystrophy type 1 (DM1) is caused by the expansion of a CTG trinucleotide repeat in the noncoding region of the DMPK gene, while facioscapulohumeral muscular dystrophy type 1 (FSHD1) is characterized by the contraction of the D4Z4 repeat array on chromosome 4q35." (PMID 39593150, 2024). "This is a dominant inherited, multi-systemic, disease due to the expansion of the CTG triplet repeat in the DMPK gene for type 1 myotonic dystrophy (DM1) and the CCTG-tetranucleotide sequence in the CNBP gene for the DM2." (PMID 38678519, 2024). "The well-known CUG-repeat containing sequence is the 3’ UTR of DMPK mRNA, where the CUG repeat is expanded from normal 5 ~ 37 repeats to mutated 50 ~ 3000 repeats in myotonic dystrophy type 1 (DM1) patients." (PMID 37202440, 2023). "The condition is caused by unstable, simple nucleotide tandem repeats in thedystrophia myotonica protein kinase (DMPK) gene for myotonic dystrophy type 1(DM1) and in the cellular nucleic acid binding protein gene (CNBP) for myotonicdystrophy type 2 (DM2)." (PMID 36177340, 2022). "Myotonic dystrophy type 1 (DM1) is an autosomal dominant genetic disorder caused by CTG's abnormal repeat expansion in the noncoding region of the dystrophia myotonic protein kinase (DMPK) gene." (PMID 35873771, 2022). "Myotonic dystrophy type 1 (DM1) is a genetic disorder caused by a (CTG) expansion in the DM protein kinase (DMPK) gene, representing the most common adult muscular dystrophy, characterized by a multisystem involvement with predominantly skeletal muscle and brain affection." (PMID 36291994, 2022). "Myotonic dystrophy type 1 (DM1) is an autosomal inherited neuromuscular disease caused by aberrant expanded trinucleotide repeats (CTG) in the 3’ untranslated region (3’UTR) of the DMPK gene." (PMID 35464065, 2022). "Myotonic dystrophy type 1 (DM1) is a chronic, multisystemic, autosomal dominant neuromuscular disorder caused by an expanded CTG repeat in the DMPK gene." (PMID 35103843, 2022).
myotonic dystrophy type 1 (continued). "Myotonic dystrophy type 1 (DM1), the most frequent inherited muscular dystrophy in adults, is caused by the CTG repeat expansion in the 3′UTR of the DMPK gene." (PMID 33530452, 2021). "Myotonic dystrophy type 1 (DM1) is an autosomal dominant hereditary disease caused by the expansion of the cytosine thymine guanine triplet repeats within the myotonic dystrophy protein of the kinase (DMPK) gene." (PMID 34955817, 2021). "It is an autosome dominant disease which is associated with abnormal expansion of the repeated cytosine-thymine-guanine (CTG) in the 3′-untranslated regions in dystrophia myotonica-protein kinase (DMPK) gene on chromosome 19q13.3." (PMID 32050933, 2020). "Apart from classical distal myopathies, impaired stress granule formation has also been identified as a relevant pathogenic factor in myotonic dystrophy type 1 (DM1), a DNA-expansion disorder caused by expanded CTG repeats in the DMPK gene." (PMID 32823799, 2020). "Myotonic dystrophies types 1 (DM1) and 2 (DM2) are autosomal dominant, multisystemic diseases, due to CTG- or CCTG-repeat expansion mutations in DMPK and CNBP, respectively." (PMID 32373059, 2020). "Myotonic dystrophy type 1 (Steinert disease) is due to a large expansion of a CTG trinucleotide repeat in the DMPK gene." (PMID 32673314, 2020). "Increasing evidences indicate that in Myotonic Dystrophy type 1 (DM1 or Steinert disease), an autosomal dominant multisystem disorder caused by a (CTG)n expansion in DMPK gene on chromosome 19q13." (PMID 33117249, 2020). "The estimated number of CTG repeats in the DMPK gene was abnormally expanded to about 600 repeats, suggesting a diagnosis of the classical type of myotonic dystrophy type 1." (PMID 33033872, 2020). "Drosophila models exist for multisystemic disorders such as Myotonic Dystrophy Type 1 (DM1) that is caused by CTG expansions in the Dystrophia Myotonica Protein Kinase (DMPK) gene leading to the sequestration of RNA binding proteins such as MBNL1 in nuclear foci." (PMID 32630420, 2020). "Myotonic dystrophy type 1 (DM1) is an autosomal dominant trinucleotide repeat disorder, caused by an expanded CTG repeat in the 3’ UTR of the dystrophia myotonica protein kinase (DMPK) gene." (PMID 32287265, 2020). "Myotonic dystrophy type 1 (DM1) is caused by expansion of the DMPK CTG trinucleotide repeat." (PMID 31316546, 2019). "The unconjugated DMPK ASO was evaluated in clinical trials for the treatment of myotonic dystrophy type 1." (PMID 31127296, 2019). "In the same study, we compared alternative splicing in RE+ FECD to the well-characterized mis-splicing due to a similar CTG repeat expansion in the untranslated region of the DMPK gene in myotonic dystrophy, type 1." (PMID 29966009, 2018). "Myotonic dystrophy 1 and 2 (DM1, DM2) are caused by unstable CTG or CCTG repeats within the gene DMPK or CNBP (ZNF9), respectively." (PMID 29910736, 2018). "Myotonic dystrophy type 1 (DM1), the most common form of muscular dystrophy in adults, is caused by toxic RNAs produced from the mutant DM protein kinase (DMPK) gene." (PMID 26901467, 2016). "Myotonic dystrophy type 1 (DM1) is an inherited autosomal dominant disease that is caused by the presence of multiple “CUG” repeats within the 3′ UTR of myotonic dystrophy protein kinase (DMPK) pre-mRNA." (PMID 23896598, 2013). "In patients with myotonic dystrophy type 1 (DM1), an adult-onset form of muscular dystrophy caused by the expression of mutant transcripts from the DMPK gene containing expanded CUG repeats, CELF1 is aberrantly up-regulated in the heart and skeletal muscles." (PMID 21541285, 2011). "The CTG repeat in the DMPK gene of myotonic dystrophy type 1 patients is highly unstable in muscle cells." (PMID 22028931, 2011). "Myotonic Dystrophy type 1 (DM1) is a degenerative neuromuscular disease characterised by a large CTG repeat expansion situated in the 3’ UTR of the DMPK gene." (PMID 20714308, 2010).
myotonic dystrophy type 1 (continued). "Myotonic dystrophy types 1 and 2 are forms of muscular dystrophy resulting from large expansions of nucleotide repeats within noncoding regions of DMPK and ZNF9, respectively." (PMID 20174632, 2010). "Myotonic dystrophy 1 (DM1) is an autosomal dominant neuromuscular disease involving the expansion of unstable CTG repeats in the 3′ untranslated region (UTR) of the DM protein kinase (DMPK) gene." (PMID 18270582, 2008). "Myotonic dystrophy type 1 (DM1), the most common adult-onset neuromuscular disease, is caused by a microsatellite (CTG)n repeat expansion in the 3′ untranslated region (UTR) of the dystrophia myotonica protein kinase (DMPK) gene." (PMID 40606545, 2025). "Similarly, analysis regarding expansion of repetitive elements, for example, the one causing myotonic dystrophy type 1 (OMIM #160900, DMPK-gene) was introduced in 2019." (PMID 40620702, 2025). "No individual carried a pathogenic STR expansion (e.g., in DMPK gene causing myotonic dystrophy type 1, associated with hypogammaglobulinemia)." (PMID 40226629, 2025). "DMPK is involved in muscle function and myotonic dystrophy type 1 (DM1)." (PMID 41172738, 2025). "Myotonic dystrophy type 1 (DM1) is one of the most common muscular dystrophies in adults and is caused by a trinucleotide cytosine-thymine-guanine (CTG) repeat expansion in the dystrophia myotonica protein kinase (DMPK) gene." (PMID 39463607, 2024). "Myotonic dystrophy type 1 (DM1), commonly known as Steinert’s disease (OMIM #160900), is the most common muscular dystrophy among adults, caused by an unstable expansion of a CTG trinucleotide repeat in the 3′ untranslated region (UTR) of DMPK." (PMID 36768526, 2023). "Myotonic dystrophy type 1 (DM1) is caused by a highlystructuredRNA repeat expansion, r(CUG)exp, harbored in the 3′untranslated region (3′ UTR) of dystrophia myotonica proteinkinase (DMPK) mRNA and drives disease through a gain-of-functionmechanism." (PMID 37521782, 2023). "Myotonic Dystrophies type 1 and type 2 are complex genetic diseases caused by unstable CTG expansions (from 37 to up to several thousand repeats) in the 3′UTR of the DMPK gene (DM1) and CCTG expansions in the first intron of the CNBP (also known as ZNF9) gene (DM2)." (PMID 36142405, 2022). "Myotonic dystrophy type 1 (DM1) is a common muscular dystrophy involving a toxic RNA gain-of-function resulting from the expansion of CTG trinucleotides in the 3′ UTR of the myotonic dystrophy protein kinase (DMPK) gene." (PMID 36362145, 2022). "Myotonic dystrophy type 1 (DM1) is an autosomal dominant, multisystemic disease caused by an expansion of a CTG trinucleotide repeat in the 3′ untranslated region of the dystrophia myotonica protein kinase gene (DMPK; OMIM 160900)." (PMID 35126292, 2021). "For example, neuron-iPSCs were generated from patients affected by myotonic dystrophy 1 (DM1), caused by an expansion of the CTG trinucleotide repeats in the 3′ untranslated region of the dystrophia myotonica protein kinase (DMPK) gene." (PMID 33937264, 2021). "The absence of severe fixed weakness or muscle wasting distinguishes NDMs from dystrophic myotonias, such as myotonic dystrophies type 1 and type 2 (DM1 and DM2 due to DMPK and CNBP mutations, respectively), which present with both progressive muscle weakness and multisystem involvement." (PMID 34140924, 2021). "Myotonic dystrophy type 1 (DM1) is an autosomal dominant disease caused by a trinucleotide (i.e., CTG) repeat expansion in the 3′ untranslated region of the dystrophia myotonica protein kinase (i.e., DMPK) gene on chromosome 19q13.3." (PMID 31849810, 2019). "Background/Objectives: Myotonic dystrophy type 1 (DM1) is a rare, multisystemic disorder caused by an expanded (CTG)n repeat in the DMPK gene." (PMID 41465188, 2025).